ESPN (espin)
Description:
Multifunctional actin-bundling protein. Plays a major role in regulating the organization, dimension, dynamics and signaling capacities of the actin filament-rich microvilli in the mechanosensory and chemosensory cells. Required for the assembly and stabilization of the stereociliary parallel actin bundles. Plays a crucial role in the formation and maintenance of inner ear hair cell stereocilia (By similarity). Involved in the elongation of actin in stereocilia. In extrastriolar hair cells, required for targeting MYO3B to stereocilia tips, and for regulation of stereocilia diameter and staircase formation.
Synonyms: DFNB36; LP2654; DFNA91; USH1M
Tractability: PROTAC: its protein half-life has been measured.
Gene: Protein-coding gene on chromosome 1 (6,424,776 to 6,461,367, forward strand). Ensembl gene ENSG00000187017.
Subcellular location: Cytoplasm, cytoskeleton; Cell projection, stereocilium; Cell projection, microvillus
Subcellular location (Human Protein Atlas): Vesicles
Pathways (Reactome):
Sensory Perception: Sensory processing of sound by inner hair cells of the cochlea; Sensory processing of sound by outer hair cells of the cochlea
Gene Ontology:
Molecular function: actin filament binding; SH3 domain binding; actin binding
Biological process: microvillar actin bundle assembly; actin filament bundle assembly
Cellular component: microvillus; stereocilium; brush border; cytoplasm; filamentous actin; stereocilium tip; actin-based cell projection; cluster of actin-based cell projections; cytoskeleton
Genetic constraint (gnomAD): Loss-of-function variants: 65 observed, 61.15 expected, observed/expected ratio (o/e) 1.06, 90% interval 0.87 to 1.31. The upper end of that interval is the gene's LOEUF score, 1.31, which puts it in group 5 of 6, group 1 being the genes least tolerant of losing a copy. Missense variants: 1,034 observed, 942.48 expected, observed/expected ratio (o/e) 1.1, 90% interval 1.04 to 1.15. Synonymous variants: 439 observed, 420.16 expected, observed/expected ratio (o/e) 1.04, 90% interval 0.96 to 1.13.
Gene-disease validity (ClinGen):
ClinGen rates the evidence that ESPN causes each of these diseases.
nonsyndromic genetic hearing loss (autosomal recessive): Definitive. A disease characterized by hearing loss that is not part of a larger syndrome.
nonsyndromic genetic hearing loss (autosomal dominant): Limited.
Homologues: Orthologues: macaque ESPN (98% identical), chimpanzee ESPN (94% identical), guinea pig ESPN (86% identical), pig ESPN (86% identical), dog ESPN (86% identical), rat Espn (83% identical), mouse Espn (77% identical), zebrafish espn (59% identical), Drosophila melanogaster f (27% identical), Caenorhabditis elegans ipla-3 (14% identical). Paralogues in human: ESPNL (29% identical).
Diseases named in the same sentence as ESPN in open-access papers:
ESPN is named in the same sentence as 14 diseases in open-access papers, as found by Europe PMC text mining. Sharing a sentence is not in itself a finding about the gene and the disease. The quoted sentences say what the papers report.
deafness (12 papers, 2005 to 2025). An inherited or acquired condition characterized by the complete loss of the ability to hear from one or both ears. "A frameshift mutation affecting the espin C-terminal actin-bundling module causes deafness and vestibular behavioral defects accompanied by stereocilium shortening and disorganization in the jerker mouse." (PMID 35353227, 2022). "The functional relevance of Espin has been largely documented in hair cells of the inner ear in which Espin loss is associated with incorrect lengthening of stereocilia, which leads to degeneration of hair cells and deafness." (PMID 31002663, 2019). "A large circular or C-shaped actin bundle formed in the nucleus when LLC-PK1 cells expressed cytomegalovirus promoter-driven GFP–espin-2B constructs bearing the jerker deafness mutation." (PMID 24424026, 2014). "The most interesting gene in this region is ESPIN, which has previously been shown to be involved in deafness in mice and two frameshift mutations in the gene have just recently been associated with deafness in two consanguineous families." (PMID 15713228, 2005). "Genes from the CAPZA family were involved with the regulation of the growth of actin filament and associated deafness (e.g., PLS1, LHFL5, OTOG, ESPN, and ESPNL)." (PMID 41465109, 2025). "The variants of TMC1, ESPN, POU3F4, MYH14, EYA1, and MR-RNR1 genes followed those from the top tier deafness genes in the order of frequency as a molecular etiology of severe-to-profound NSHL in Vietnamese." (PMID 30733538, 2019). "The del(GJB6-D13S1830), SERPINB6, TMIE, COCH, ESPN, ACTG1, GJB3, and KCNQ4 mutations were infrequently associated with deafness in the Moravian-Silesian population." (PMID 30344259, 2018). "PDZD7 may act as a modifier gene for USH, but HARS, ABHD12, CIB2, CEP250, CEP78, ESPN, and ARSG could be grouped in a separate syndromic “deaf–blindness” category, to avoid diagnostic pitfalls and misinformation during genetic counseling for Usher syndrome." (PMID 35353227, 2022). "For example, it could be hypothesised that transcripts of deafness-associated genes, MSRB3, ESPN, and WHRN, all in possession of extreme A + U/C + G compositions, are likely to be sensitive to any drug-mediated global dysregulation of expression, with ototoxicity a potential outcome." (PMID 40341320, 2025). "Segdups, defined as regions with > 95% homology, are features that are causally implicated in recurrent CNVs mediated by NAHR and were identified in seven deafness genes: TSPEAR (4 segdups), OTOA, STRC, MYO3A, ESPN, OTOGL, CACNA1D." (PMID 24963352, 2014). "The Jerker mouse model shows that stereocilia degenerate in the absence of Espin, resulting in HC dysfunction and deafness, and it has been shown that Espin is important for the growth and maintenance of the actin‐based protrusions of inner ear neuroepithelial cells." (PMID 37084708, 2023).
hearing loss (3 papers, 2016 to 2023). "Class III myosins (Myo3) and actin-bundling protein Espin play critical roles in regulating the development and maintenance of stereocilia in vertebrate hair cells, and their defects cause hereditary hearing impairments." (PMID 26785147, 2016).
melanoma (3 papers, 2018 to 2021). A malignant, usually aggressive tumor composed of atypical, neoplastic melanocytes. "Recent study showed that miR-612 negatively regulated the expression of ESPN in melanoma cells. miR-612 targeted the 3′-UTR of ESPN mRNA to inhibit ESPN gene expression that suppressed melanoma cell growth, migration and invasion." (PMID 30618491, 2018). "Mechanistically, ESPN inhibition in melanoma promotes p21 and p27 protein expressions and arrests cell cycle at G1 phase." (PMID 30618491, 2018). "The expression of espin in melanoma mice is significantly increased by immunohistochemistry." (PMID 34194957, 2021). "Knockdown of espin leads to significantly less metastasis of melanoma cells." (PMID 34194957, 2021). "Enhanced ESPN expression in melanoma accelerates tumor growth, migration, and invasion." (PMID 30618491, 2018). "Recent few studies show that ESPN regulates metastasis and cell proliferation in melanoma." (PMID 30618491, 2018). "In human cancers, ESPN plays a growth and metastatic regulator for melanoma." (PMID 30618491, 2018). "Furthermore, espin is targeted by miR-612 to inhibit the invasive phenotype of melanoma cells." (PMID 34194957, 2021). "Thus, espin represents a new biomarker for melanoma progression." (PMID 34194957, 2021). "Depletion of endogenous ESPN in melanoma cells causes cell growth reduction in vitro and in vivo; moreover, ESPN inhibition attest cell cycle at G1 phase via increasing p21 and p27 and decreasing Erk and AKT activities in melanoma cells." (PMID 30618491, 2018).
Ataxia (1 paper, 2017). Ataxia refers to impaired coordination of voluntary muscle movement. "Since spine maturation is also disrupted due to reduced Espin expression, synaptogenesis and electrophysiological properties of the mutant PCs become abnormal, causing ataxia in the DKO mutants." (PMID 28516904, 2017).
Retinal dystrophy (1 paper, 2025). Retinal dystrophy is an abnormality of the retina associated with a hereditary process. "ESPN: A homozygous deletion in the ESPN gene was found in a large, extended, consanguineous Pakistani family with prelingual hearing loss, vestibular dysfunction, and retinal dystrophy consistent with a diagnosis of Usher syndrome type I." (PMID 40149483, 2025).
tumor (5 papers, 2017 to 2025). "We then generated the espin OE B16-F10 cell line and examined the role of espin in tumor growth using a subcutaneous tumor model." (PMID 40185977, 2025). "We evaluated the expression profiles of espin in tumor and normal samples with the TCGA and GTEx databases and found that espin was elevated in multiple tumors." (PMID 40185977, 2025). "Besides, expressions of ENPP2 and ETS1 were significantly decreased in BRCA tumor samples, and ESPN and RIIAD1 were significantly elevated in BRCA tumor samples compared with adjacent normal samples." (PMID 32412047, 2020). "We did not observe any association between ESPN expression with any clinicopathologic parameters including age, primary tumor location, histologic grading, T classification, N classification, and 7th AJCC Stage." (PMID 30618491, 2018). "We thus set to investigate whether espin modulated tumor metastasis." (PMID 40185977, 2025). "In accordance with our finding that espin did not promote cell proliferation, we observed that the subcutaneous tumor weight remained similar between control and espin OE groups." (PMID 40185977, 2025). "CpG islands located at RIIAD1, ENPP2, ESPN, and ETS1, were hyper-methylated in BC tumor." (PMID 38082340, 2023).
cancer (4 papers, 2017 to 2025). A tumor composed of atypical neoplastic, often pleomorphic cells that invade other tissues. "Moreover, the higher expression level of espin was associated with lower overall survival, especially within the first 150 months, suggesting a correlation between espin and cancer aggressiveness during the early period." (PMID 40185977, 2025). "Altogether, the contribution of espin to cancer progression is independent of the modulation of invadopodia formation or cell survival under fluid shear stress." (PMID 40185977, 2025). "Moreover, espin contributes to cancer metastasis without affecting cell proliferation, invadopodia assembly or cell survival under fluid shear stress." (PMID 40185977, 2025).
infection (4 papers, 2018 to 2024). The state of being infected such as from the introduction of a foreign agent such as serum, vaccine, antigenic substance or organism. "We found it curious that espN overexpression in the ΔespM strain phenocopied the ΔespMΔespN strain during laboratory growth and macrophage infection." (PMID 38445877, 2024). "In vivo, we found that ΔespN had 3.4-fold reduced burden compared to WT at 5 days post-infection (P = 0.00012) and was complemented by constitutive expression of the espN gene." (PMID 38445877, 2024). "Defining the regulatory targets of EspN, as well as how the EspM and EspN regulons compare, will likely require measuring global gene expression during specific stages of infection." (PMID 38445877, 2024). "From these data, we conclude that EspN is required for M. marinum growth and during macrophage infection." (PMID 38445877, 2024). "Our findings suggest that EspN is required for ESX-1 function during infection possibly due to transcriptional regulation of ESX-1 genes." (PMID 38445877, 2024). "Then, cells from the five infection schemes were analyzed for the co-expression of Brn3c and Espin as shown in Figure 3E1,E2." (PMID 34940631, 2021). "Only the percentage of Espin-positive cells in the J2+D1-5d infection scheme was higher than that of the cells infected with NC-shRNA (p < 0.05)." (PMID 34940631, 2021). "In our experimental set-up we confirmed the expression of MYOSIN VIIA protein and MYOSIN VIIA, POU4F3 and ESPIN mRNAs after 12 days of infection." (PMID 29979748, 2018). "EspN was likewise necessary for robust infection in zebrafish larvae." (PMID 38445877, 2024). "However, EspM obscures the regulatory role of EspN under laboratory conditions and during macrophage infection." (PMID 38445877, 2024). "Notably, transcriptional profiling of M. tuberculosis from infected macrophages isolated from mouse infections revealed significant upregulation of the espN (Rv1725c) transcript compared to broth-grown culture." (PMID 38445877, 2024). "Together, these data demonstrate a critical role for EspN and the ESX-1 transcriptional network during infection." (PMID 38445877, 2024). "Our data propose a model where EspM and EspN counterbalance to regulate ESX-1 gene transcription both in the laboratory and during infection." (PMID 38445877, 2024). "Here, we discovered and characterized EspN, a transcriptional regulator of the ESX-1 system that is essential for infection." (PMID 38445877, 2024). "EspN is also independently required for M. marinum growth within and cytolysis of macrophages, similar to the ESX-1 genes, and for disease burden in a zebrafish larval model of infection." (PMID 38445877, 2024). "espN deletion did not have regulatory phenotypes under laboratory conditions or during macrophage infection under the conditions we tested." (PMID 38445877, 2024). "The rate of Brn3C/Espin double positive cells from the J2-5d and D1-5d infection schemes was not significantly different from that of the cells infected with NC-shRNA (Figure 3E1,E2)." (PMID 34940631, 2021). "To test how EspN and EspM impact transcription during infection, we infected RAW 264.7 macrophages with M. marinum strains lacking espM, espN, or both espM and espN." (PMID 38445877, 2024).
bacterial infection (1 paper, 2024). "The structural similarity to the important virulence factors CNF(Y) and RTX suggests that EspN and EspS may be two classes of undiscovered virulence factors that may play important roles in the pathogenesis of bacterial infections." (PMID 39457374, 2024).
ESPN also shares sentences with these, for which no sentence is quoted: esophageal squamous cell carcinoma (1 paper); Hearing impairment (1); microtia (1); Usher syndrome (1); Usher syndrome type 1 (1).